NUP153 (nucleoporin 153)
Description:
Component of the nuclear pore complex (NPC), a complex required for the trafficking across the nuclear envelope. Functions as a scaffolding element in the nuclear phase of the NPC essential for normal nucleocytoplasmic transport of proteins and mRNAs. Involved in the quality control and retention of unspliced mRNAs in the nucleus; in association with TPR, regulates the nuclear export of unspliced mRNA species bearing constitutive transport element (CTE) in a NXF1- and KHDRBS1-independent manner. Mediates TPR anchoring to the nuclear membrane at NPC. The repeat-containing domain may be involved in anchoring other components of the NPC to the pore membrane. Possible DNA-binding subunit of the nuclear pore complex (NPC). (Microbial infection) Interacts with HIV-1 capsid protein P24 and thereby promotes the integration of the virus in the nucleus of non-dividing cells (in vitro). (Microbial infection) Binds HIV-2 protein vpx and thereby promotes the nuclear translocation of the lentiviral genome (in vitro).
Synonyms: HNUP153; N153
Tractability: Small molecule: a structure with a bound ligand is known. PROTAC: UniProt records ubiquitination sites on it; ubiquitination databases record sites on it; its protein half-life has been measured.
Gene: Protein-coding gene on chromosome 6 (17,614,707 to 17,706,935, reverse strand). Ensembl gene ENSG00000124789.
Subcellular location: Nucleus; Nucleus membrane; Nucleus, nuclear pore complex
Subcellular location (Human Protein Atlas): Nuclear membrane
Pathways (Reactome):
Disease: Defective TPR may confer susceptibility towards thyroid papillary carcinoma (TPC); HCMV Early Events; HCMV Late Events; NEP/NS2 Interacts with the Cellular Export Machinery; NS1 Mediated Effects on Host Pathways; Nuclear import of Rev protein; Rev-mediated nuclear export of HIV RNA; SARS-CoV-2 activates/modulates innate and adaptive immune responses; Transport of Ribonucleoproteins into the Host Nucleus; Viral Messenger RNA Synthesis; Vpr-mediated nuclear import of PICs
Metabolism of RNA: Transport of Mature mRNA Derived from an Intronless Transcript; Transport of Mature mRNA derived from an Intron-Containing Transcript; Transport of the SLBP Dependant Mature mRNA; Transport of the SLBP independent Mature mRNA; snRNP Assembly; tRNA processing in the nucleus
Metabolism of proteins: SUMOylation of DNA damage response and repair proteins; SUMOylation of DNA replication proteins; SUMOylation of RNA binding proteins; SUMOylation of SUMOylation proteins; SUMOylation of chromatin organization proteins; SUMOylation of ubiquitinylation proteins
Metabolism: IP3 and IP4 transport between cytosol and nucleus; IP6 and IP7 transport between cytosol and nucleus; IPs transport between nucleus and cytosol; Regulation of Glucokinase by Glucokinase Regulatory Protein
Cell Cycle: Nuclear Pore Complex (NPC) Disassembly
Cellular responses to stimuli: Regulation of HSF1-mediated heat shock response
Immune System: ISG15 antiviral mechanism
Gene Ontology:
Molecular function: identical protein binding; molecular condensate scaffold activity; protein binding; protein-membrane adaptor activity; structural constituent of nuclear pore
Biological process: amyloid fibril formation; negative regulation of RNA export from nucleus; nuclear pore complex assembly; nucleocytoplasmic transport; protein import into nucleus; RNA export from nucleus
Cellular component: membrane; nuclear envelope; nuclear inclusion body; nuclear membrane; nuclear periphery; nuclear pore; nuclear pore nuclear basket; nucleus; nucleoplasm
Genetic constraint (gnomAD): Loss-of-function variants: 11 observed, 105.74 expected, observed/expected ratio (o/e) 0.1, 90% interval 0.064 to 0.17. The upper end of that interval is the gene's LOEUF score, 0.17, which puts it in group 1 of 6, group 1 being the genes least tolerant of losing a copy. Missense variants: 1,596 observed, 1,588 expected, observed/expected ratio (o/e) 1, 90% interval 0.96 to 1.05. Synonymous variants: 569 observed, 586.87 expected, observed/expected ratio (o/e) 0.97, 90% interval 0.9 to 1.04.
Homologues: Orthologues: chimpanzee NUP153 (99% identical), macaque NUP153 (97% identical), pig NUP153 (87% identical), dog NUP153 (87% identical), rabbit NUP153 (84% identical), guinea pig NUP153 (83% identical), mouse Nup153 (82% identical), rat Nup153 (82% identical), tropical clawed frog nup153 (46% identical), zebrafish nup153 (41% identical), Drosophila melanogaster Nup153 (27% identical). Paralogues in human: NUP214 (17% identical), POM121 (15% identical), POM121C (14% identical), NPAP1 (13% identical), POM121L2 (11% identical), POM121L12 (2% identical).
Diseases named in the same sentence as NUP153 in open-access papers:
NUP153 is named in the same sentence as 59 diseases in open-access papers, as found by Europe PMC text mining. Sharing a sentence is not in itself a finding about the gene and the disease. The quoted sentences say what the papers report.
HIV-1 infection (20 papers, 2012 to 2025). The type species of lentivirus and the etiologic agent of acquired immunodeficiency syndrome (AIDS). "Thus, while NUP153 may bind more than one HIV-1 determinant, our results are consistent with a direct interaction between NUP153C and viral CAN underlying the requirement for NUP153 during HIV-1 infection." (PMID 24130490, 2013). "WT HIV-1 infection is diminished in cells depleted of Nup153 but retains greater infectivity in Nup155-knockdown cells." (PMID 37355754, 2023). "Of all the nucleoporins depleted from human cells in large-scale screens, NUP153 was consistently identified as being important for HIV-1 infection." (PMID 36040047, 2022). "CA-Nup153 binding during HIV-1 infection was inferred via the restriction activity of an artificial TRIM5-Nup153896–1475 fusion construct that harbored the Nup153 FG domain." (PMID 33477441, 2021). "CPSF6 directly interacts with the viral CA via the same binding pocket as NUP153, and when re-localized to the cytoplasm, inhibits HIV-1 infection." (PMID 30084827, 2018). "The effects of NUP153 depletion on HIV-1 infection in CsA treated cells were also similar to the effects of RANBP2 depletion, rendering HIV-1WT infection CsA dependent (as previously reported) and exaggerating the CsA dependence of HIV-1A94E in HeLa cells." (PMID 30084827, 2018). "The exception to this general finding was that CsA dramatically reduced the deleterious effects of RANBP2 and NUP153 depletion on WT HIV-1 infection of HeLa cells." (PMID 30084827, 2018). "Depletion of Nup153 added an additional block to HIV-1 infection on top of T5Cyp-mediated restriction but, notably, resulted in a greater rescue of infection relative to control DsRed KD cells." (PMID 27107820, 2016). "In the case of Nup153, the ability to support HIV-1 infection maps to the viral CA protein, and structural studies have found that the phenylalanine/glycine repeats (FG repeats) present on Nup153 are able to bind a conserved “pocket” on assembled CA." (PMID 27327622, 2016). "We conclude that although NUP153C in the context of the Trim5 protein likely engages HIV-1 CA earlier than endogenous NUP153 protein, the novel fusion nonetheless affords the analysis of the NUP153-CA interaction in the context of HIV-1 infection." (PMID 24130490, 2013). "At least for TNPO3, NUP358, and NUP153, such concerns are somewhat assuaged by subsequent findings which demonstrated that the knockdowns affected HIV-1 infection in relatively specific, CA-dependent manners." (PMID 24103892, 2013). "PF74 and CPSF6 accordingly each competed with NUP153C for binding to the HIV-1 CA pocket, and significantly higher concentrations of PF74 were needed to inhibit HIV-1 infection in the face of Trim-NUP153C expression or NUP153 knockdown." (PMID 24130490, 2013). "Indeed, in cells depleted of Nup35, POM121, or Nup153, a partial restoration of WT HIV-1 infection is observed after coordinate knockdown of CPSF6, especially in Nup35 and POM121 knockdown cells." (PMID 37355754, 2023). "In addition, studies showed HIV-1 infection is dependent on Nucleoporin 153 (Nup153) binding, which has been subsequently linked to nuclear import." (PMID 33557422, 2021). "Collectively, these data suggest that NUP153 or CPSF6 might have roles in HIV-1 infection beyond their interactions with their binding pocket in CA." (PMID 30084827, 2018). "Notably, the widely reported effects of RANBP2 and NUP153 on HIV-1 infection of HeLa cells were less evident in HT1080 cells." (PMID 30084827, 2018). "Like RANBP2, NUP153 has been reported to specifically enhance HIV-1 infection." (PMID 30084827, 2018). "Put another way, CsA rescued WT HIV-1 infection of HeLa cells when RANBP2 or NUP153 were depleted." (PMID 30084827, 2018). "In contrast to Nup153, the role of Nup358 in HIV-1 infection remains less clear." (PMID 27327622, 2016). "We confirmed that depletion of Nup153 reduced HIV-1 infection in T5Cyp cells." (PMID 27107820, 2016).
HIV-1 infection (continued). "In this study we unravel the distinct roles of Nup153 and Tpr in HIV-1 infection." (PMID 25744187, 2015). "NUP153, CPSF6 and PF74 utilize a distinct sub-set of residues within this site, providing a molecular basis for their associations with capsid and the resulting effects on HIV-1 infection." (PMID 25356722, 2014). "Depletion of Nup153 inhibits HIV-1 infection and CA is involved in this dependence." (PMID 23883001, 2013). "We previously showed that the viral capsid (CA) protein mediated the dependency on cellular nucleoporin (NUP) 153 during HIV-1 infection, and now demonstrate a direct interaction between the CA N-terminal domain and the phenylalanine-glycine (FG)-repeat enriched NUP153 C-terminal domain (NUP153C)." (PMID 24130490, 2013). "As we previously found CA to be the dominant viral determinant of the requirement for NUP153 during HIV-1 infection, we tested whether a physical interaction between NUP153 and HIV-1 CA exists." (PMID 24130490, 2013). "Although these data do not quantitatively address potential CA oligomerization-based affects on NUP153C binding, the relatively robust interaction with CAN suggests that NUP153 may efficiently engage monomeric CA during HIV-1 infection." (PMID 24130490, 2013). "HIV-1 infection was impaired by Nup358/RanBP2, Nup153, or Nup160 knockdown." (PMID 22928108, 2012). "We found that although all studied nucleoporins impaired HIV-1 infection upon depletion, only two (Nup358/RanBP2, and Nup153) were involved in nuclear import and indeed only one (Nup153) showed any evidence of actual participation in translocation through the NPC." (PMID 23049930, 2012). "Notably, coordinate depletion of Nup35 and Nup153 potently impaired WT HIV-1 infection." (PMID 37355754, 2023). "Furthermore, it was predicted that naturally occurring polymorphisms in human and nonhuman primates would disrupt NUP153 interaction with capsid, potentially protecting certain populations from HIV-1 infection." (PMID 36040047, 2022). "Similar to Nup153 and CPSF6, TRIM5 fusions to the FG-rich portion of POM121 inhibit HIV-1 infection." (PMID 37355754, 2023). "Nup35, Nup153, Nup358, and POM121 depletion were observed to inhibit WT HIV-1 infection but affected N74D and P90A HIV-1 infection to a lesser degree." (PMID 37355754, 2023). "In contrast, HIV-1 infection in HeLa cells exhibited a marked requirement for specific nucleoporins, particularly NUP358 and NUP153 and the transport receptor TNPO3, in agreement with previous observations." (PMID 30496303, 2018). "A number of phenotypic similarities suggest the roles of TNPO3, NUP153, NUP358, CPSF6, and CypA during HIV-1 infection are interrelated." (PMID 24103892, 2013). "Interestingly, CsA treatment also rescues HIV-1 infection from RANBP2 (and NUP153) knockdown in some cell types, suggesting that CA interactions with both CypA and the RANBP2-Cyp domain determine the requirement for RANBP2." (PMID 39853118, 2025). "Because Nup35 and POM121 depletion affected WT HIV-1 infection but not CA mutant HIV-1 in a pattern similar to Nup153 and Nup358, we focused efforts on these two Nups." (PMID 37355754, 2023). "Notably, depletion of CypA not only restored HIV-1 infection in Nup35-knockdown cells but similarly restored infection in POM121-knockdown cells and partly restored infection in Nup153-knockdown cells." (PMID 37355754, 2023). "Cellular proteins CPSF6, NUP153 and SEC24C play crucial roles in HIV-1 infection." (PMID 36202818, 2022). "Host proteins CPSF6, NUP153, and SEC24C are vital for HIV-1 infection." (PMID 36202818, 2022). "However, the inherent dependence of HIV-1 infection upon NUP358, NUP153 and TNPO3 in HeLa cells confounds this analysis since their depletion results in less efficient infection regardless of MX2 expression." (PMID 30496303, 2018). "Our microscopy data suggest that Nup153 acts indirectly by anchoring Tpr to the NPC, while Tpr may have a more active role on LEDGF/p75 and HIV-1 infection." (PMID 25744187, 2015).
HIV-1 infection (continued). "Interestingly, codepletion of Nup153 and transportin-SR2 (TRN-SR2) yielded synergistic effects, that outweighed those calculated based on individual knockdowns, indicating potential interdependent roles for these factors during HIV-1 infection." (PMID 22928108, 2012). "Interestingly, Matreyek and Engelman have reported that co-depletion of Nup153 and TNPO3 yielded synergistic inhibitory effects on HIV-1 infection, underscoring the fact that simultaneous targeting of multiple HDFs might be a potentially useful therapeutic/preventive approach." (PMID 23028330, 2012). "Engagement of CPSF6 is not required for HIV-1 infection in transformed cell lines but is tightly correlated with dependence on the nuclear entry cofactors TNPO3, NUP153 and NUP358." (PMID 25356722, 2014).
viral infection (4 papers, 2013 to 2024). "In addition to its cellular functions, TPR has been implicated in viral infection, as it is required for viral mRNA export, distinct from other basket NUPs, such as NUP153 and NUP50." (PMID 39080077, 2024). "During viral infection, NUP153 interacts with the HIV-1 capsid protein, contributing to the entry of the intact capsid into the nucleus." (PMID 39080077, 2024). "Genetic variation in host factors hijacked by viruses can protect from viral infection and the NUP153 gene is evolving rapidly in primates." (PMID 36040047, 2022). "These binding phenotypes moreover correlated with the requirement for endogenous NUP153 protein during virus infection." (PMID 24130490, 2013). "While originally described to support CPSF6 binding, the high degree of amino acid conservation within this region of CA amongst primate lentiviruses likely also reflects the requirement for binding to NUP153 during virus infection." (PMID 24130490, 2013).
prostate carcinoma (3 papers, 2018 to 2025). A carcinoma that arises from epithelial cells of the prostate gland. "Here we report about the new role of Nup153 in a hormone-driven activation cascade, involving eNOS and NO production, which contributes to a transcriptional program associated with prostate cancer." (PMID 29963256, 2018). "In our study, it also emerged that p300 was associated with Nup153 in prostate cancer cells." (PMID 29963256, 2018). "In the present work, we have characterized the role of Nup153 in a cellular model of prostate cancer (PCa)." (PMID 29963256, 2018). "Our findings unveil Nup153 as a novel component of the estrogen-dependent multimeric complex, thus representing a potential therapeutic candidate in prostate cancer." (PMID 29963256, 2018). "The analysis of several immortalized cell lines derived from freshly explants of prostate cancer specimens showed that Nup153 protein was higher and present in multimeric complexes with eNOS and ERβ as compared to normal/hyperplastic prostate epithelial cells." (PMID 29963256, 2018). "We first evaluated whether Nup153 silencing by siRNA could affect migration and clonogenic ability of prostate cancer cells." (PMID 29963256, 2018). "Another important finding of our work regards the positive effect of Nup153 on the clonogenic capacity of prostate cancer cells thus suggesting that targeting this protein could represent a possible therapeutic strategy to counteract tumor growth." (PMID 29963256, 2018). "Thus, in conclusion, the multiple roles played by Nup153 in prostate cancer cells makes it a potential powerful target to counteract tumor aggressiveness." (PMID 29963256, 2018). "Our results suggest Nup153 as potential therapeutic target in prostate cancer." (PMID 29963256, 2018). "Notably, in lung adenocarcinoma (LUAD) and LUSC, NUP153 expression was significantly negatively correlated with immune-related genes; whereas, in pancreatic ductal adenocarcinoma (PAAD) and prostate cancer (PRAD), a positive correlation was observed." (PMID 40607419, 2025). "In addition, eNOS and ERβ nuclear localization was lost upon siNup 153 regardless of E2 treatment, suggesting that Nup153 is a key regulator of prostate cancer cell function and of the nuclear translocation of these proteins in response to hormone stimulus." (PMID 29963256, 2018).
thyroid cancer (3 papers, 2021 to 2025). "We found six RBPs (AZGP1, IGF2BP2, MEX3A, NUDT16, NUP153, USB1) independently associated with prognosis of patients with thyroid cancer according to univariate and multivariate Cox proportional hazards regression models." (PMID 33816259, 2021). "First, we transfected NUP153 specific siRNA into thyroid cancer cell line TPC1 and BCPAP to decrease the expression of NUP153." (PMID 33816259, 2021).
cardiovirus infection (2 papers, 2019 to 2022). "Most importantly, FG-NUPs that had previously been shown to be hyperphosphorylated during cardiovirus infection: NUP62, NUP98, NUP153 and NUP214 exhibited statistical significance." (PMID 36508477, 2022). "For example, enterovirus and cardiovirus infections alter NPC composition to relocalize some nuclear proteins to the cytoplasm, whereas enteroviruses are known to induce degradation of nucleoporins Nup62, Nup98, and Nup153." (PMID 31875556, 2019).
colorectal cancer (2 papers, 2025). A primary or metastatic malignant neoplasm that affects the colon or rectum. "NUP153 showed significant expression variation across cancers, with high levels in cholangiocarcinoma, colorectal cancer, and head and neck squamous cell carcinoma." (PMID 40607419, 2025).
glioblastoma (2 papers, 2024 to 2025). The most malignant astrocytic tumor (WHO grade IV). "Additionally, spatial transcriptomics data analysis showed that in CRC, liver hepatocellular carcinoma (LIHC), head and neck squamous cell carcinoma (HNSC), glioblastoma (GBM), and LUSC, NUP153 expression was positively correlated with neutrophil spatial distribution." (PMID 40607419, 2025).